CD44 (CD44 molecule (IN blood group))
Diseases named in the same sentence as CD44 in open-access papers (continued):
Sharing a sentence is not in itself a finding about the gene and the disease.
pancreatic cancer (continued). "Proteomic analysis reveals the selective enrichment of known exosome markers and also signaling proteins involved in pancreatic cancer progression (KRAS, CD44, and EGFR) in oncogenic exosomes compared to exosomes from non-malignant cells." (PMID 32974169, 2020). "Compared with control group, significant higher frequencies of memory CD4+ T cells (CD4+ CD44+ CD62L−) and CD8+ T cells (CD8+ CD44+ CD62L−) in tumor and tumor‐draining LN regions were observed in the subcutaneous pancreatic tumors." (PMID 32508058, 2020). "Pancreatic cancer stem cells do exist and express specific markers including CXCR4, ABCG2, and CD44." (PMID 32210079, 2020). "The same scenario happened in CD24/44 stem cell system in PanIN/IPMN, which was reported as pancreatic cancer stem cell (CSC) markers, CD24/CD44 population decreased significantly in IPMN than in PanIN when treated with Akti." (PMID 32266133, 2020). "Bera and colleagues demonstrated that gemcitabine treatment induces pancreatic cancer cell lines to undergo an EMT process and convert from CD44 negativity to CD44 positivity." (PMID 31992334, 2020). "Therefore, targeting CD44 positive pancreatic cancer cells might enhance therapies effectiveness." (PMID 31049070, 2019). "In pancreatic cancer, cells that express the cell-surface proteins CD13339 or the combination of CD44/CD24/EpCAM40 have been shown to exhibit characteristics of stem cells." (PMID 31101868, 2019). "Transcriptional factor Snail1 is a CD44 downstream target that regulates MMP14 expression and in turn MMP14 is required for pancreatic cancer invasion." (PMID 29747682, 2018). "In pancreatic cancer, the oncogenic lncRNA MALAT-1 contributes to the expression of the cancer stem cell marker CD133, CD44, CD24, and aldehyde-dehydrogenase." (PMID 29967761, 2018). "Sorted pancreatic tumour cells ALDH-positive, dual CD24- and CD44-positive, and triple CD24-, CD44-, and ALDH-positive were previously demonstrated to be highly tumourigenic compared to unsorted tumour cells." (PMID 28569190, 2017). "AURKA inhibition reduced the levels of N-cadherin, CD44, vimentin, MMP-2, Slug, and Snail, but increased E-cadherin levels in pancreatic cancer cell lines." (PMID 28193222, 2017). "Pancreatic CSCs express specific markers, including CD24, CD44, CD133, EpCAM, CXCR4, c-Met, and CD166, at levels substantially different from the bulk pancreatic cancer cells." (PMID 28845161, 2017). "Evidence from recent work suggests that pancreatic cancer comprises several subsets of CSCs, including ESA+CD24+CD44+ cells, CD133+CXCR4+ cells, and c-Met+ subset cells, which are defined by their self-renewal ability, tumorigenicity, and metastatic ability." (PMID 28032597, 2017). "The authors confirmed that CD44 and CD133 expression is present in normal and inflammatory pancreatic tumors." (PMID 28659655, 2017). "In an orthotopic pancreatic tumor model, CDF also inhibited the expression of EZH2, NOTCH-1, CD44, EpCAM, and NANOG." (PMID 28611316, 2017). "Taken together, our results suggest that miR-23a partially promotes pancreatic cancer EMT and metastasis by targeting ESRP1 and regulating CD44 splicing as well as FGFR2 IIIb and FGFR2 IIIc mRNA levels." (PMID 29137308, 2017). "In our study, we characterized two pancreatic cancer cell lines (MIA PaCa-2 and PANC-1), using the expression of reported CSC surface markers including CD44, CD24, ESA, and CD133." (PMID 29179494, 2017). "CD44+CD24+EpCAM+, CD133+, ALDH+ are markers for prospectively identifying pancreatic cancer stem cells." (PMID 26673007, 2016). "To address the expression of the putative CSC markers CD24, CD44, EpCAM, CD133, and nestin in pancreatic cancer, we used three cell lines (P6B, P28B, and P34B) derived from PDAC tumor tissues and three corresponding FFPE tumor samples." (PMID 27414409, 2016).
pancreatic cancer (continued). "Yet another study has shown that the cyclopamine treatment can down-regulate expressions of CD44+ and CD133+ in gemcitabine-resistant pancreatic cancer cells indicating its potential efficacy in reversing gemcitabine resistance in pancreatic cancer." (PMID 31656694, 2016). "CD44 and phosphorylated AKT (p-AKT) is a potentially interesting prognostic marker and therapeutic target in pancreatic cancer." (PMID 26666511, 2015). "The expression of CD44 and p-AKT has been reported to correlate with poor prognosis of pancreatic cancer in most literatures." (PMID 26666511, 2015). "According to the histochemical results, pancreatic cancer patients manifesting high levels of OPN/LC3/ALDH1 and OPN/CD44/CD133 had poor survival." (PMID 26458814, 2015). "In pancreatic cancer, CD133+CXCR4+ population and CD44+Met+ population show increased metastatic potential when compared to the respective negative population." (PMID 26597727, 2015). "LC3 expression positively correlated with the expression of CSC markers aldehyde dehydrogenase 1 (ALDH1), CD44, and CD133 in pancreatic cancer tissues." (PMID 26458814, 2015). "Pancreatic cancer cells with a high expression of both c-MET and CD44 were shown to have a greater tumorigenic potential." (PMID 24823486, 2014). "In summary, we identified a highly tumorigenic subpopulation of pancreatic cancer cells expressing the cell surface markers CD24, CD44 and ESA in pancreatic adenocarcinoma cell line PANC-1." (PMID 24521357, 2014). "CD44, a transmembrane glycoprotein with binding domains for hyaluronic acid which is crucial component of ECM, is highly expressed in pancreatic cancer." (PMID 24505326, 2014). "We identified a highly tumorigenic subpopulation of pancreatic cancer cells expressing the cell surface markers CD24, CD44 and ESA in pancreatic adenocarcinoma cell line PANC-1." (PMID 24521357, 2014). "Cancer Stem Cells (CSCs) of human pancreatic cancer cell line PANC-1 were processed for CD24, CD44 and ESA multi-colorstaining, and sorted out on a BD FACS Aria II machine." (PMID 24521357, 2014). "Subsequently, CD133, CD44, CD24 were selected as CSC markers in many solid tumors, including pancreatic carcinoma." (PMID 24689055, 2014). "Quantitative RT-PCR was performed to measure Bmi1 levels in the CSCs (cell surface markers CD44+CD24+ESA+) and compared to the remaining bulk tumor cells harvested from the human pancreatic cancer xenografts grown in NOD-SCID mice." (PMID 23437065, 2013). "Several markers, including CD44, ALDH and CD133, have been used successfully to isolate CSCs from breast, prostate, colorectal, glioblastoma, and pancreatic cancers, and CD133 has previously been identified as a putative CSC marker for ATC." (PMID 23724124, 2013). "Further experimentation indicate that silencing the miR-373 activator, CREB, in pancreatic cancer cells also leads to increased expression of TP53INP1 and CD44, respectively." (PMID 23857777, 2013). "The current study identified a novel ZIP4-CREB-miR-373 signalling axis that promotes pancreatic cancer growth, through silencing on key tumour suppressor molecules including TP53INP1, LATS2 and CD44." (PMID 23857777, 2013). "The small population of pancreatic cancer cells that expressed ALDH, CD44, and CD24 exhibited the highest tumorigenic potential in vivo, although the differences with cells expressing only ALDH or CD44 and CD24 were not statistically significant." (PMID 24213498, 2012). "Using the pancreatic cancer cell line PANC-1, it was also found that CD44+CD24+ cells have a higher in vivo tumorigenic potential than cells expressing either marker, which are in turn more tumorigenic than CD44−CD24− cells." (PMID 24213498, 2012). "Inhibition of the Hedgehog pathway with cyclopamine reduced the expression of supposed CSC markers CD44, CD133 and ALDH in pancreatic cancer cell lines." (PMID 24213498, 2012).
pancreatic cancer (continued). "Pancreatic cancer stem cells have been characterized by stem cell markers CD133+ and CD44+/CD24+/EpCAM+ (epithelial adhesion molecule)/ESA (epithelial specific antigen)." (PMID 22570653, 2012). "This study demonstrates a central role of Notch signalling pathway in pancreatic cancer pathogenesis and identifies an effective approach to inhibit selectively EMT and suppress tumorigenesis by eliminating pancreatic tumor initiating CD44+/EpCAM+ cells." (PMID 23094026, 2012). "In pancreatic cancer, cells based on specific cell-surface markers (i.e. CD24+CD44+ESA+ and CD133+ cells) have been reported to possess CSC characteristics." (PMID 22894607, 2012). "Decreased IGF-1R expression inhibited the growth of the PANC-1 pancreatic cancer cells and increased the 3-Cl-AHPC-mediated inhibition of CD44+/CD24+sphere size." (PMID 22570653, 2012). "These authors found minimal overlap between ALDH and CD44+/CD24+ cell populations (<0.1%), suggesting the existence of at least two distinct tumor-initiating populations within human pancreatic tumors." (PMID 21695188, 2011). "Human pancreatic CSCs expressing high levels of CD133, CD24, CD44, ESA, and aldehyde dehydrogenase also express significantly more Nanog, Oct-4, Notch1, MDR1 and ABCG2 than normal pancreatic tissues and primary pancreatic cancer cells." (PMID 21304978, 2011). "Normal pancreatic tissues express very low levels of CD133, CD24, CD44, ESA, Nanog, Notch1, MDR1 and ABCG2 compared to pancreatic cancer and CSCs." (PMID 21304978, 2011). "Both CD44 and CD133 have been used as markers to identify the pancreatic cancer stem cells from human tumor tissues." (PMID 19714243, 2009). "Additionally, biomarkers such as AFP, CD44, Galectin-3, and CEA exhibit notable importance, reinforcing their relevance in pancreatic cancer detection." (PMID 40217526, 2025). "In pancreatic cancer, CSCs can be identified by specific surface markers such as CD133 and CD44." (PMID 40903212, 2025). "Both CD44 and CD24 positive pancreatic cancer cells are considered PCSCs43." (PMID 39897042, 2025). "Moreover, in pancreatic cancer xenografts, ATO in combination with gemcitabine reduced CD24−/CD44+ and ALDH1A1+ CSC populations and inhibited tumor growth." (PMID 38612911, 2024). "Furthermore, pancreatic tumors are enriched in suppressive macrophages expressing the known TSG-6 receptor, Cd44, which co-localize with TSG-6 within these tumors." (PMID 38987547, 2024). "In therapeutic applications, targeted therapy against CD44 or ABC transporter inhibitors could be used to overcome drug resistance and may be beneficial in the treatment of pancreatic cancer." (PMID 37108495, 2023). "miR-205 is downregulated in pancreatic cancer and, in an in vitro model, the overexpression of miR-205 decreased the expression of both general stemness markers such as OCT-3/4 and NANOG, and more specific pancreatic CSC markers such as CD44 and ALDH1." (PMID 38139352, 2023). "CD44 and GABRP co-expression was positively correlated in 178 pancreatic cancer patients." (PMID 35846884, 2022). "In pancreatic cancer, CD24 and CD44 are recognized as malignant CSC marker." (PMID 36430445, 2022). "Moreover, pancreatic cancer patients with high CD44V3 levels showed poor OS, which showed a more potent correlation than that of CD44." (PMID 36292918, 2022). "Patients with CD44-positive pancreatic cancer have a shorter median survival (20.3 months) than those with CD44-negative disease (25.3 months)." (PMID 36605595, 2022). "The expression of both CD44 and GABRP was upregulated in pancreatic gemcitabine resistant cells and tumor tissues compared to the null resistant cells and normal tissues, and they were significantly co-expressed in patients with pancreatic cancer." (PMID 35846884, 2022). "Moreover, a high expression level of CD44 and/or SLC16A1 was correlated with a relatively unfavorable survival in pancreatic cancer patients." (PMID 36302783, 2022).
pancreatic cancer (continued). "Targeting CD44 and GABRP may have a synergistic effect on the suppression of gemcitabine-induced resistance in pancreatic cancer." (PMID 35846884, 2022). "In our study, we found that PPARγ might diminish the PDAC stemness via decreasing the expression level of CD44 and CD133 in pancreatic cancer cells, enhancing the killing effect of Gemcitabine on pancreatic cancer cells." (PMID 35186942, 2021). "We detected the expression of several markers of cell stemness, such as CD44, CD133, OCT4, Nanog, and KLF4, to test whether the effect of Arl4c on promoting drug resistance in pancreatic cancer is attributed to its role in regulating cell stemness." (PMID 34849465, 2021). "The antitumor ether lipid edelfosine induces apoptosis in CD44+CD24+EpCAM+ pancreatic cancer stem cells (CSCs) and blocks the formation of pancreatic CSC spheroids, derived from the established human pancreatic cancer cell lines as well as from pancreatic cancer patient-derived primary cultures." (PMID 34885233, 2021). "Specifically, the pancreatic cancer stem cell surface marker c-Met reacts to secreted ligands and markers CD44 and CD24 foster intercellular interactions, thereby activating pathways such as Stat3, Notch, and β-catenin in pancreatic cancer stem cells and thus stimulating self-renewal." (PMID 33928036, 2021). "Thus, CD133, EpCAM, CD44, and CXCR4 are commonly used to isolate and examine the involvement of the CSC population in pancreatic cancer progression and constitute prime targets for the treatment." (PMID 33946266, 2021). "Bitter melon water extract could inhibit CD44+/CD24+/EpCAMhigh CSC populations, decrease CSC markers SOX2, OCT4, NANOG and CD44 and enhance gemcitabine sensitivity in pancreatic cancer models." (PMID 32726914, 2020). "CD44 expression was not different in IL-17A treated Panc02 murine pancreatic cancer cells compared to the controls (1.73% vs. 1.38%)." (PMID 32210079, 2020). "However, other studies reported that FOXO3a knockdown suppressed CD44 expression and CSC properties in pancreatic cancer cells." (PMID 31296961, 2020). "SOX2 knockdown in pancreatic cancer cells leads to an inhibition of cell growth, while SOX2 transfection promotes cell entry into S-phase and proliferation, and it also increases the expression levels of CSC pancreatic ALDH1, ESA, and CD44 markers." (PMID 32523653, 2020). "Expression of CD24, CD44, and ESA are enriched in pancreatic cancer stem cells." (PMID 30382189, 2019). "Besides, it has been reported that CD44, c-Jun, and BRD4 promote pancreatic cancer cell proliferation and metastasis and induce chemotherapy resistance." (PMID 31718704, 2019). "CDF could inhibit sphere formation capacity of pancreatic cancer cell lines and inhibit the expression of the CSC markers CD44 and EpCAM." (PMID 28611316, 2017). "In this study, we determined the regulatory relationship between miR-23a and ESRP1, and proposed that miR-23a may promote pancreatic cancer EMT and metastasis via regulating CD44 splice isoform switching." (PMID 29137308, 2017). "Furthermore, in the other pancreatic cancer cell line of HPAC, the expressions of stemness related genes and PAUF were upregulated in CD44+CD24+ESA+ than in CD44-CD24-ESA- HPAC cells." (PMID 29100320, 2017). "Pancreatic cancer sphere cultured from the CFPAC-1 cells showed elevated expression of PAUF and pluripotent stemness genes (Oct4, Nanog, Stat3, and Sox2), and the mRNA of PAUF were increased in CD44+CD24+ESA+ pancreatic CSCs." (PMID 29100320, 2017). "EMT has also been demonstrated to correlate with CD24+CD44+ and CD133+ cells in pancreatic cancer, providing pancreatic cancer stem cells with a strong migratory capacity, while maintaining their ability to multiply and thus allowing the production of progenies during metastasis." (PMID 26884312, 2016).
pancreatic cancer (continued). "Pancreatic CSCs have been identified both in patient tumors by their expression of the cell surface markers ESA (epithelial surface antigen; CD326), CD44 and CD24 and in murine pancreatic tumors with a slightly different panel of markers (CD44+, CD133+, Sca1+)." (PMID 27330806, 2016). "Thus far, two CSC populations in pancreatic cancer have been shown to be metastatic, CD133+CXCR4+ and Met+CD44+." (PMID 25829252, 2015). "In human pancreatic cancer tissue, lymph node metastasis overexpressed CD44 while there was less expression of CD44 in negative lymph node metastasis." (PMID 26666511, 2015). "Cisplatin treatment resulted in an average increase of 77 % in the CD44+CD117+ population, likely because these cells are resistant to cell death from chemotherapy, similar to the enrichment observed in pancreatic cancer ALDH+-expressing cells following cisplatin treatment." (PMID 26718286, 2015). "Since there is a partial overlap between CD44+/CD24+/ESA+ and CD133+ pancreatic cancer cells, it is conceivable that a combination of the markers may help to mark more pure CSCs than a single marker." (PMID 26458814, 2015). "Pancreatic cancer stem cells (PCSC) were identified in 2007, when several groups demonstrated the presence of CD24, CD44, epithelial specific antigen (ESA) triple positive markers or CD133 positive cells had the ability to initiate tumor formation in animals at very low numbers." (PMID 26597727, 2015). "In fact, the expression patterns of CD44 in pancreatic carcinoma have not been systematically investigated at the mRNA level." (PMID 24708709, 2014). "CD133+ and CD24+CD44+ESA+ cells are considered pancreatic cancer stem cells, and the proliferation of CD133+ but not CD24+CD44+ESA+ cells was selectively inhibited by low concentrations of metformin." (PMID 23667692, 2013). "We found that silencing of TP53INP1, LATS2 and CD44 in MIA PaCa-2 cells significantly increased tumour growth compared with the vector control cells, indicating a bona fide tumour suppressor function in pancreatic cancer cells." (PMID 23857777, 2013). "Taken together, this study demonstrates the central role of Notch signalling pathway in pancreatic cancer pathogenesis independent of their tumorigenicity and that pancreatic tumor initiating CD44+/EpCAM+ cells are down regulated by GSI." (PMID 23094026, 2012). "Moreover, RARbeta in blood correlated with TNFRSF10C, CD44, ACIN1, APC, p16 and LINE-1 in pancreatic tumor tissue." (PMID 22629410, 2012). "Notably, the CD44+CD24+ESA+ cells represent a particularly small cell fraction in human pancreatic adenocarcinomas, as this subset comprises less than 1% of the pancreatic cancer cell population." (PMID 24213498, 2012). "Interestingly, there does appear to be some degree of overlap between CD44+CD24+ESA+ and CD133+ pancreatic cancer cells." (PMID 21188169, 2011). "Furthermore, miRNAs belonging to the miR-200 family, such as miR-200a, play a role in regulating stemness in pancreatic cancer by reducing the expression of CSC markers and EMT-related genes such as CD24, CD44, EpCAM, as well as the EMT markers N-cadherin, ZEB1, and vimentin." (PMID 38139352, 2023). "Additionally, miR-205 is downregulated in pancreatic cancer and its overexpression decreases the expression of both general stemness markers such as OCT-3/4 and NANOG and more specifically pancreatic CSC markers, including CD44 and ALDH1." (PMID 38139352, 2023). "Our data suggest that direct cell-to-cell transfer of biomolecules play roles in providing a survival advantage to cancer cells during chemotherapy and targeting CD44 and/or MCT1 may be a plausible strategy to overcome drug resistance and metastasis in pancreatic tumors." (PMID 36302783, 2022). "Pancreatic cancer is associated with many CSCs markers that are negative prognostic factors and associated with tumor recurrence and clinical progressions, such as CD133, CD24, CD44, CXCR4, and ESA." (PMID 35892853, 2022).